DANCR (differentiation antagonizing non-protein coding RNA)
Diseases named in the same sentence as DANCR in open-access papers (continued):
Sharing a sentence is not in itself a finding about the gene and the disease.
tumor (83 papers, 2016 to 2026). "Recent studies have revealed a significant association between DANCR expression and tumour angiogenesis." (PMID 38877534, 2024). "Among the identified tumour hallmarks, DANCR is intricately linked to abnormal proliferation, invasion, metastasis, angiogenesis, the inflammatory phenotype, energy metabolism reprogramming, and resistance of tumour cells to apoptosis." (PMID 38877534, 2024). "Aberrant expression of DANCR in various cancers is associated with oncogenic or tumor suppressive mechanisms that are hallmarks of cancer, such as cell proliferation, invasion, and metastasis." (PMID 33980320, 2021). "Specifically, the lncRNA DANCR is overexpressed in stem cell-like HCCs and is associated with tumor recurrence and decreased survival." (PMID 34572776, 2021). "Pearson Chi square tests displayed that higher DANCR expression was positively associated with larger tumor size (p = 0.015) and advanced FIGO stage (p = 0.025)." (PMID 32123519, 2020). "Current evidences suggested that DANCR was associated with important cellular mechanisms and functioned as tumorigenesis, colonization, tumor invasion, metastasis, proliferation, migration, apoptosis, disease progression and prognosis in numerous cancers." (PMID 33123287, 2020). "The increased expression of DANCR is found to be associated with advanced tumor progression and poor prognosis in colon cancer patients." (PMID 29416741, 2018). "The expression levels of DANCR were significantly associated with tumor size, TNM stage, lymphatic metastasis and invasion depth." (PMID 29416741, 2018). "We found that the serum levels of DANCR were associated with tumor size (P = 0.000), lymphatic metastasis (P = 0.000), invasion depth (P = 0.017) and TNM stage (P = 0.000)." (PMID 29416741, 2018). "Notably, significant associations have been observed between DANCR expression levels and the tumour size, TNM stage, lymph node metastasis, and invasion depth in patients with GC." (PMID 38877534, 2024). "Importantly, abnormal up-regulation of DANCR has been revealed to be linked with advanced tumor progression of CC." (PMID 32423468, 2020). "Furthermore, PCR assays of the resected tumour tissues showed that DANCR expression was negatively associated with miR‐496." (PMID 29266795, 2018). "In addition, we showed that the expression of SALL4was positively associated with that of DANCR in the tumor tissues of GC patients." (PMID 29416741, 2018). "Recent studies have demonstrated that DANCR was overexpressed in major types of cancers, and its expression was closely associated with clinicopathological characteristics, including lymphatic metastasis, distant metastasis and tumor-node-metastasis (TNM) stage." (PMID 33123287, 2020). "Interestingly, higher level of DANCR was demonstrated to be associated with bigger tumor size." (PMID 30518934, 2018). "Research has shown that DANCR expression in GC tissues surpasses that in adjacent tissues, with increased DANCR levels promoting tumour growth and correlating with reduced patient survival rates." (PMID 38877534, 2024). "Studies have revealed that the upregulation of DANCR in various tumours promotes proliferation by modulating the cell cycle." (PMID 38877534, 2024). "Within tumour biology, DANCR exerts regulatory control over crucial processes such as proliferation, invasion, metastasis, angiogenesis, inflammatory responses, cellular energy metabolism reprogramming, and apoptosis." (PMID 38877534, 2024). "This article offers a comprehensive review and elucidation of the primary functions and molecular mechanisms through which DANCR influences tumours." (PMID 38877534, 2024). "This review focuses on the biological function, regulatory mechanism, and clinical significance of DANCR in tumours." (PMID 38877534, 2024). "The outcomes revealed that DANCR knockout significantly impeded tumour growth, including tumour dimensions and mass." (PMID 38877534, 2024).
tumor (continued). "Utilizing a male BALB/c nude mouse allogeneic transplantation model, they revealed that depleting DANCR inhibited the weight, volume, size, and proliferation of tumours derived from GC MGC-803 cells in vivo." (PMID 38877534, 2024). "Using female BALB/c nude mice, they established a subcutaneous CRC mouse model and showed that DANCR knockout significantly impeded CRC tumour growth." (PMID 38877534, 2024). "Current studies suggest that DANCR functions as a tumour suppressor in RCC, with its expression downregulated in RCC tissues." (PMID 38877534, 2024). "Aberrant DANCR expression has been observed in various tumour types, prompting extensive investigations into its functional roles and molecular mechanisms." (PMID 38877534, 2024). "For example, the RAS and MYC oncogenes can contribute to tumor incidence and progression through the lncRNA Orilnc1 and DANCR, respectively." (PMID 37915049, 2023). "Although DANCR knockdown suppressed cell proliferation in vitro, more significant efficiency of tumor suppression was found in the xenograft model." (PMID 37215458, 2023). "DANCR overexpression promoted OS cell line proliferation, migration, and invasion and promoted tumor growth and metastasis in vivo." (PMID 36831169, 2023). "Later, both the oncogenic and tumor-suppressive roles of DANCR have been identified across cancers, participating in modulating tumor cell growth, stemness-like properties, EMT, and chemoresistance." (PMID 35936737, 2022). "Tens of tumor suppressor miRNAs have been shown to be sponged by DANCR, leading to release of miRNA targets from their inhibitory effects." (PMID 35590326, 2022). "Given that DANCR binds to LIPG in tumor cells, we next investigated if functional DANCR mediates LIPG expression." (PMID 35954428, 2022). "While DANCR over-expression in mouse xenograft tumours formed from the injection of aggressive MDA-MB-231 cells decreased metastasis formation and spread, its knockout under in vitro conditions in MCF10A cells induced EMT, cell migration and invasion." (PMID 33807045, 2021). "Results demonstrated that miR-145, a tumor suppressor involved in tumor angiogenesis, is a direct target of DANCR promoting the derepression of vascular endothelial growth factor (VEGF) in ovarian cancer." (PMID 34204094, 2021). "Another study found that the lncRNA DANCR is associated with the EMT, leading to tumor recurrence and metastasis 24,25." (PMID 34093785, 2021). "Our data have validated that KLF5 knockdown accelerated GC cell autophagy in vitro and repressed tumor growth in vivo by regulating the DANCR/miR-194/AKT2 axis." (PMID 34548487, 2021). "It was also demonstrated that DANCR mediated apoptosis by modulating MALAT1, with the expression of MALAT1 being downregulated upon DANCR knockdown in both cell lines and xenograft tumour tissues." (PMID 33807355, 2021). "Research suggests that DANCR most likely has tumour-suppressive function because of its low activity in BC cell lines and tissues." (PMID 33807045, 2021). "Previous evidence has suggested the tumor-initiating activities of DANCR in CRC, which was realized through sponging miR-577 as a ceRNA25." (PMID 34548487, 2021). "It is suggested that DANCR serve as a tumor promoter or suppressor, representing a promising cancer biomarker or therapeutic target in various cancers." (PMID 34722539, 2021). "The silencing efficiency of DANCR expression was validated in the xenograft tumors, indicating the difference in tumor size was specifically correlated with DANCR expression level." (PMID 33414433, 2021). "Increasing studies suggest that the dysregulation of DANCR plays critical roles in cancer cell proliferation, apoptosis, migration, invasion, and chemoresistance in vitro and tumor growth and metastasis in vivo." (PMID 34722539, 2021). "DANCR expression is correlated with pathogenesis and progression and is predictive of the outcome of several neoplasms." (PMID 33968736, 2021).
tumor (continued). "In terms of tumor formation, our study found that silencing of DANCR inhibited the growth rate and the KI67-positive rate of the xenograft tumors in vivo (all p < 0.05)." (PMID 32423468, 2020). "In terms of tumor metastasis, it was shown that the formation of metastatic nodules in liver and lung were reduced when DANCR was down-regulated (all p < 0.05)." (PMID 32423468, 2020). "We demonstrated that downregulation of DANCR had tumor‐suppressive functions in PC cells by enhancing miR‐33b expression." (PMID 31515968, 2020). "Experiments with xenograft models revealed that while ectopic expression of DANCR promotes, DANCR KO suppresses tumor growth." (PMID 31804607, 2020). "Down-regulation of DANCR led to reduced proliferation, viability, invasion, migration, and resistance to death of CC cells, as well as reduced tumor formation and metastasis in vivo." (PMID 32423468, 2020). "Increasing evidence suggests that lncRNA DANCR functions as a tumor promoter in numerous types of tumor." (PMID 31515968, 2020). "DANCR overexpression in BXPC-3 cells significantly increased tumor growth rate and tumor size as compared to vector control." (PMID 31804607, 2020). "Together, our results suggest that ZNF750 plays a tumor suppressive role via DANCR/miR-4707-3p/FOXC2 axis that works in a ceRNA manner in ESCC." (PMID 32341351, 2020). "Through in silico analysis, we identified tumor suppressor miR-216a as a potential binding partner to DANCR, and confirmed this binding through coimmunoprecipitation and luciferase-reporter assays." (PMID 33302540, 2020). "Future studies should focus on characterizing the role of DANCR in CSCs to determine its impact on chemoresistance, tumor initiation, and metastasis in NSCLC." (PMID 33302540, 2020). "DANCR's distinct expression in tumor cells and collective involvement in pro-tumor pathways make it a promising therapeutic target for broad cancer treatment." (PMID 31799189, 2019). "Generally, DANCR exerts multiple regulatory functions on tumor progression of numerous cancers, revealing its role as an important pro-tumor regulator." (PMID 31799189, 2019). "The decreased expression of DANCR was confirmed in sh-DANCR-expressing tumor tissues compared with control tumors." (PMID 31383847, 2019). "Further study indicated that DANCR overexpression significantly promoted cell proliferation and invasion in vitro and contributed to tumor growth in vivo." (PMID 30910842, 2019). "DANCR can acts as competitive endogenous RNA (ceRNA) and competitively bind tumor suppressive miRNAs to restore the functions of target oncogenic mRNAs." (PMID 31799189, 2019). "The in vivo results further demonstrated that inhibition of DANCR prevented the tumor growth, which indicates the oncogenic role of DANCR in TSCC tumorigenesis." (PMID 31827393, 2019). "In this study, we investigated the expression of DANCR in the tumor tissues and serum of GC patients and analyzed the correlation between DANCR expression levels and the clinicopathological characteristics." (PMID 29416741, 2018). "To validate that DANCR/RXRA/PIK3CA signaling pathway regulates TNBC tumor growth, we down-regulated RXRA and overexpressed PIK3CA in MDA-MB-231 and MDA-MB-468 cells with a RXRA shRNA or a PIK3CA vector." (PMID 30518934, 2018). "DANCR was found to be significantly upregulated in TNBC tumor tissues compared with that in normal breast tissues." (PMID 30518934, 2018). "In this study, we investigated the expression of DANCR in the tumor tissues and serum of GC patients, as well as the relationship between DANCR expression levels and the clinicopathological properties of GC." (PMID 29416741, 2018). "In conclusion, we demonstrate in this study that DANCR is upregulated in the tumor tissues and serum of GC patients." (PMID 29416741, 2018). "Remarkably, knockdown of DANCR was significantly decreased TNBC tumor growth compared with controls." (PMID 30518934, 2018).
tumor (continued). "To explore the role of RXRA in DANCR-mediated TNBC tumor growth, we first assessed RXRA protein and expression in DANCR depletion TNBC cells." (PMID 30518934, 2018). "The expression level of DANCR was significantly higher in tumor tissues than that in adjacent normal tissues (P < 0.001) and 80.0% (52/65) GC tissues showed increased expression of DANCR compared to the adjacent normal tissues." (PMID 29416741, 2018). "Recently, the potential role of DANCR in cancer has been reported in several studies; however, these studies showed that DANCR plays opposite roles depending on the tumour type." (PMID 29266795, 2018). "Meanwhile, further analysis by Pearson Chi-Square test or Fisher’s Exact Test indicated higher expression of DANCR was correlated with bigger tumor size (≥ 5 cm), advanced staging (IIB/III) and distant metastasis." (PMID 29753317, 2018). "We also revealed that the knockdown of DANCR suppressed tumour cell proliferation, migration and invasion both in vivo and in vitro and promoted cell apoptosis." (PMID 29266795, 2018). "The GC patients with high expression levels of DANCR were prone to have large tumor (P = 0.001), lymph node metastasis (P = 0.000), invasion depth (P = 0.028) and advanced TNM stage (P = 0.009)." (PMID 29416741, 2018). "Conversely, DANCR knockdown successfully attenuated the stemness and in vivo interference with DANCR action, leading to decreased tumor cell survival, tumor shrinkage, and improved mouse survival." (PMID 26978351, 2016). "We further examined the role of DANCR in metastasis using a tumor metastasis mouse model." (PMID 41602364, 2026). "With regard to CRC, previous studies have shown that DANCR might act as an oncogenic long non-coding RNA affecting tumor progression and FOXC2 has been implicated as an oncogene promoting tumor invasion and metastasis." (PMID 41039543, 2025). "Extensive research has revealed the intricate mechanisms through which DANCR promotes tumour development, involving interactions such as a ceRNA targeting microRNAs, the modulation of mRNA or protein activities, initiation of signalling cascades, and epigenetic modulation." (PMID 38877534, 2024). "The regulation of DANCR, a typical lncRNA, in tumours involves a multitude of intricate mechanisms." (PMID 38877534, 2024). "Targeting DANCR expression in xenograft tumours delays tumour growth." (PMID 38877534, 2024). "The biological function of DANCR in tumours encompasses various critical aspects." (PMID 38877534, 2024). "The contradictory functions of lncRNA DANCR may be explained by its ambiguous role in regulation of the complex networks of oncogenes and tumor suppressors resulting in a cancer type‐dependent outcome." (PMID 35150011, 2022). "DANCR enhances tumor cell proliferation, invasion, and metastasis in TNBC." (PMID 35954428, 2022). "DANCR is an oncogenic lncRNA which induces several cancer-promoting effects, such as promotion of angiogenesis and epigenetic silencing of tumor-suppressors; it also regulates cancer-promoting signaling pathways such as the Wnt/β-catenin, JAK/STAT, Notch, and PI3K/AKT pathways." (PMID 36497269, 2022). "Moreover, bulk of evidence from investigations in xenograft models of cancer firmly supports the role of DANCR in induction of tumor growth." (PMID 35590326, 2022). "Collectively, these results suggest that a direct interaction between LIPG and DANCR may impact LIPG expression in tumor cells." (PMID 35954428, 2022). "DANCR can promote tumor progression by inducing the epithelial–mesenchymal transition (EMT)." (PMID 35954428, 2022). "Future investigations using xenografted tumor model with nude mice would bring more profound significance by investigating whether DANCR blocking reverses Ara‐C resistance in AML cell." (PMID 33638615, 2021). "The role of DANCR in paclitaxel treatment was also revealed that the upregulation of DANCR inhibited the expression of miR-135a, which could sensitize tumour cells in paclitaxel chemotherapy." (PMID 33968736, 2021).
tumor (continued). "DANCR silencing in HCC cells downregulates the expression of several stemness-associated genes, including CD133, CD90, and EpCAM, and decreases the number and dimension of tumor spheroids." (PMID 34572776, 2021). "DANCR interference may spark interest from a therapeutic point of view, as suggested by two HCC animal models where DANCR knockdown with a lentivirus-mediated approach reduced tumor growth, lung metastases, and improved survival." (PMID 34572776, 2021). "Furthermore, in xenograft tumor tissues, DANCR knockdown also dramatically impaired MALAT1 expression." (PMID 33414433, 2021). "Its expression was positively associated with tumor size, lymph node metastasis, invasion depth, and TNM stage of GC patients, suggesting that DANCR may correlate to the malignant progression of GC." (PMID 34722539, 2021). "For example, DANCR has been proven to participate in several cancer pathological processes, including tumor cell proliferation, invasion, metastasis, and chemo-resistance, and it may serve as a therapeutic target." (PMID 33767996, 2021). "Furthermore, we found that there was reciprocal repression between DANCR and miR‐33b expression, and this ensured the miR‐33b‐mediated tumor‐suppressive effects of DANCR in PC cells." (PMID 31515968, 2020). "High expression level of DANCR was positively associated with clinical grading and tumor size, but not with age, sex, isocitrate dehydrogenase (IDH), and 6-methyl-guanine methyl transferase (MGMT)." (PMID 32099526, 2020). "Likewise, quite similar with our findings, it has been documented that silencing of DANCR promoted CC cell apoptosis while inhibited tumor growth." (PMID 32423468, 2020). "Therefore, it is likely that miR-216a normally keeps Wnt signaling in check, but DANCR overexpression in NSCLC effectively blocks the tumor-suppressive function of miR-216a." (PMID 33302540, 2020). "By contrast, DANCR KO suppressed tumor growth and tumor size for three different numbers of cells." (PMID 31804607, 2020). "Besides, inhibition of DANCR limited tumor growth by regulating miR-135a-5p and BMI1 expression in vivo." (PMID 32099526, 2020). "Furthermore, DANCR KO suppressed the number of tumor spheres and these spheres were much smaller than vector control." (PMID 31804607, 2020). "miR-216a is a common tumor suppressive miRNA and downstream target of DANCR." (PMID 31799189, 2019). "In conclusion, this present study develops a novel insight that the TSCC tumor progression may be regulated by DANCR/miR-135a-5p/KLF8 axis." (PMID 31827393, 2019). "Moreover, the results of qRT-PCR also displayed that LV-sh-DANCR was able to decrease DANCR level and increase miRNA-216a-5p level in tumors, proving that DANCR expression level had close relationships with tumor growth and migration." (PMID 30910842, 2019). "Xenografted tumor growth using nude mice was performed to examine the role of DANCR in vivo." (PMID 31827393, 2019). "DANCR is a typical oncogenic lncRNA, overexpressed in various tumor cells." (PMID 31799189, 2019). "A new lncRNA, DANCR, has been reported to function as a regulator of different tumour types, but its role in NSCLC remains unknown." (PMID 29266795, 2018). "This evidence confirms that DANCR may play a tumour suppressor role by sponging miR‐496, which in turn affects its target, mTOR." (PMID 29266795, 2018). "Furthermore, the knockdown of DANCR reduced tumour volumes in vivo compared with those of the control group." (PMID 29266795, 2018). "Recently, many studies demonstrated that DANCR might act as an oncogenic lncRNA in tumor progression." (PMID 29301870, 2018). "In vivo animal studies conformed that DANCR knockdown retarded tumor growth." (PMID 29416741, 2018). "However, due to the molecular and phenotypic heterogeneity within and between different tumor types, mechanism explorations are required to elucidate the precise biological behaviour of DANCR in tumors, especially TNBC." (PMID 30518934, 2018).